NPM1 (nucleophosmin 1)
Diseases named in the same sentence as NPM1 in open-access papers (continued):
Sharing a sentence is not in itself a finding about the gene and the disease.
acute promyelocytic leukemia (41 papers, 2010 to 2026). An aggressive form of acute myeloid leukemia (AML), characterized by arrest of leukocyte differentiation at the promyelocyte stage, due to a specific chromosomal translocation t(15;17) in myeloid cells. "The combination of all-trans-retinoic acid (ATRA) and arsenic trioxide (ATO), a curative treatment for acute promyelocytic leukemia, leads to the degradation of NPM1c, inducing apoptosis and cell differentiation in NPM1-mutated cells." (PMID 32545659, 2020). "GAB2 is likewise overexpressed in many human AMLs with mutations in NPM1 and/or signaling genes, and also in acute promyelocytic leukemia initiated by PML::RARA; the PML::RARA fusion protein may activate GAB2 by directly binding to its 5′ flanking region." (PMID 40773291, 2025). "CD33 is highly expressed in acute promyelocytic leukemia (APL), NPM1-mutated AML, and FLT3/ITD mutated AML, whereas expression is usually low in leukemias with core-binding factor translocations." (PMID 36276074, 2022). "It has been proposed that the synergy of ATRA and ATO reverses the characteristic disorganization of promyelocytic leukemia (PML) bodies, as also observed in all types of NPM1-mutated AML, apart from APL." (PMID 40647396, 2025). "NPM1 mutations are most frequently detected in the M4 and M5 subtypes of AML but are rarely found in acute promyelocytic leukemia (APL)." (PMID 36824144, 2023). "The CD33 expression level appears linked to the differentiation status of the leukemia clone (e.g., high level is seen in acute promyelocytic leukemia; APL), the cytogenic profiles and to certain mutations, such as NPM1 and FLT3/ITD." (PMID 35690610, 2022). "Notably, a significant subset of NPM1-mutated AML cases also exhibit HLA-DR negativity, classifying them as “double-negative”, and mimicking, therefore, the CD34− HLA-DR− immunophenotype of acute promyelocytic leukemia (APL)." (PMID 39457595, 2024). "However, there are certain leukemia cases, for instance, acute promyelocytic leukemia (APL) patients with mutations in PML‐RARα, NPM1, and FLT3‐ITD fusion genes, and CML patients with BCR‐ABL1 gene, show significant resistance to chemotherapeutic drugs, leading to disease progression and even death." (PMID 36705414, 2023). "In fact, NPM1 mutants can impede the formation of acute promyelocytic leukemia (APL) nuclear bodies (NBs), which in turn are regulators of mitochondria fitness and key senescence effectors." (PMID 36008542, 2022). "Similar to promyelocytic leukemia-retinoic acid receptor α (PML-RARA) rearrangement, NPM1 can also serve as a marker for the surveillance of minimal residual disease (MRD) in AML patients." (PMID 36824144, 2023). "Besides the ≥20% criterion are cases of core-binding factor (CBF)-AML, nucleophosmin 1 (NPM1)-mutated AML, or acute promyelocytic leukemia (APL); in each of them, the AML diagnosis is blast %-independent." (PMID 34288963, 2021). "In acute promyelocytic leukemia cells expressing the NPM1-retinoic acid receptor α (NPM1-RAR) fusion protein, NPM1-RAR blocked TNF-induced extrinsic apoptosis by inhibiting signaling to activate caspase-3 and -8." (PMID 27553022, 2016). "Assays have been developed for three phenotypes of particular clinical significance: NPM1, Core Bind Factor (CBF)-AML (referring to the fusions gene RUNX1::RUNX1T1 and CBFB::MYH11) and Acute Promyelocytic Leukemia (APL) (referring to the fusion gene PML::RARA)." (PMID 35892893, 2022). "The combined treatment of acute promyelocytic leukemia (APL) cells with arsenic trioxide (ATO) and all-trans retinoic acid (ATRA) has been shown to rely on the degradation of Nucleophosmin 1 (NPM1) by proteasomes." (PMID 38331801, 2024). "Importantly, PCR assays have been developed for three AML phenotypes: (i) acute promyelocytic leukemia (APL) (fusion gene PML::RARA); (ii) patients with NPM1 and CBF–AML (RUNX1::RUNX1T1 and CBFB::MYH11); and (iii) AML with fusion genes BCR::ABL1, KMT2::MLLT3, and DEK::NUP214." (PMID 37345204, 2023).
lymphoma (37 papers, 2010 to 2024). A malignant (clonal) proliferation of B- lymphocytes or T- lymphocytes which involves the lymph nodes, bone marrow and/or extranodal sites. "EML4 was the most frequent partner of ALK fusions in lung cancers, while NPM1 was the case in lymphomas." (PMID 38877018, 2024). "As only cytoplasmic NPM-ALK is catalytically active, whereas the nuclear portion is inactive because of heterodimerization with NPM1, the amount of cytoplasmic NPM-ALK is crucial for optimal lymphoma growth." (PMID 31434245, 2019). "The link between Rac1 and NPM1 was previously only described in nucleophosmin-anaplastic lymphoma kinase (NPM-ALK)-positive lymphomas." (PMID 23874639, 2013). "NPM1-mutated CAR-T cells were thus capable of killing in vivo AML cells harboring HLA-A2-positivity and NPM1 mutations, but not HLA-A2-positive lymphoma cells without NPM1-mutated protein, demonstrating killing specificity." (PMID 34502069, 2021). "Several distinct, non-NPM1, ALK fusions have subsequently been described in lymphomas and other tumor types." (PMID 26187744, 2015).
acute leukemia (35 papers, 2016 to 2026). A clonal (malignant) hematopoietic disorder with an acute onset, affecting the bone marrow and the peripheral blood. "Revumenib received approval in 2024-2025 for relapsed or refractory KMT2A-rearranged acute leukemia and NPM1-mutated AML." (PMID 41749890, 2026). "Menin inhibitors are the first targeted therapies for KMT2A-rearranged and NPM1-mutated acute leukemias, addressing a significant unmet need in these high-risk subtypes." (PMID 41749890, 2026). "Recently, inhibitors disrupting the menin-MLL interaction have demonstrated promising therapeutic potential in preclinical studies and clinical trials for treating acute leukemia with MLL-AF fusions or NPM1 mutations." (PMID 40057469, 2025). "In particular, acute leukemia with NPM1 mutations (NPM1m) and KMT2A rearrangements (KMT2Ar) represent the primary targets of this emerging drug class." (PMID 40710017, 2025). "In this scenario of rapid and interesting changes, menin inhibitors represent a novel class of drugs that have shown promising results in histone-lysine N-methyltransferase 2A (KMT2A)-rearranged (KMT2Ar) and in NPM1-mutated (NPM1mut) acute leukemias." (PMID 38651453, 2024). "It has also been granted Fast Track designation by the FDA for treating pediatric and adult patients with R/R acute leukemias that have a KMT2Ar or NPM1 mutation." (PMID 39768795, 2024). "It has also been granted Fast Track status by the FDA for treating pediatric and adult patients with R/R acute leukemias that have a NPM1 mutation or KMT2A rearrangement." (PMID 39768795, 2024). "Previous studies showed synergistic effects by combining the predecessor of revumenib, SNDX-50469 (VTP50469), with a DOT1L inhibitor in both KMT2A-rearranged and NPM1-mutated acute leukemia." (PMID 38892207, 2024). "SNDX-5613, a potent and specific Menin-MLL inhibitor, will be tested in phase I clinical trial in patients with relapsed or refractory MLL-r acute leukemias harboring or mutations in Nucleophosmin 1 (NPM1) gene (NCT04065399)." (PMID 38997742, 2024). "The cohort includes adult patients with refractory relapsed acute leukemia with KMT2A-r or NPM1 mutations." (PMID 39179671, 2024). "APL with PML::RARA fusion gene and AML with NPM1 mutation represent 2 distinct acute leukemias characterized by recurrent genetic abnormalities." (PMID 39432585, 2024). "Small-molecule–mediated inhibition of the protein‒protein interaction between Menin and MLL1 fusion proteins is a potential therapeutic strategy for patients with MLL1-r or mutated-nucleophosmin 1 (NPM1c) acute leukemia." (PMID 36841758, 2023). "Similarly, Menin inhibitors demonstrate substantial therapeutic effectiveness in treating KMT2A-rearranged and NPM1-mutated pediatric acute leukemias." (PMID 40034590, 2025). "Menin inhibitors are new and promising agents currently in clinical development that target the HOX/MEIS1 transcriptional program which is critical for leukemogenesis in histone-lysine N-methyltransferase 2A-rearranged (KMT2Ar) and in NPM1-mutated (NPM1mut) acute leukemias." (PMID 38651453, 2024). "To date, revumenib stands as the most clinically developed small molecule menin inhibitor, demonstrating promising results in the first in-human phase I/II clinical trials including relapsed or refractory pediatric and adult KMT2A-rearranged or NPM1-mutated acute leukemia patients." (PMID 38892207, 2024). "Notably, Menin inhibitors are in clinical trials for the treatment of relapsed or refractory NPM1–mutated acute leukemia and acute leukemia with MLLr and have shown on-target effects, tolerable toxicity, and promising clinical activity." (PMID 39002676, 2024). "In their recently published position statement paper, the acute leukemia working party of the EBMT recommended allogeneic HSCT in first CR for all FLT3-ITD mutated AML patients with the exception of NPM1 mutated/low FLT3-ITD allelic ratio individuals achieving an MRD-negative CR." (PMID 36831653, 2023).
acute leukemia (continued). "Menin inhibitors have entered clinical trials for histone lysine methyltransferase 2 A (KMT2A)-rearranged and nucleophosmin 1 (NPM1)-mutant acute leukemias and are demonstrating promising activity." (PMID 42103719, 2026). "This phase I trial investigated the safety of revumenib in combination with chemotherapy (FLA regimen) in both adults and children with KMT2A-r, NUP98-r, or NPM1-m acute leukemia." (PMID 41154380, 2025). "The menin small molecule inhibitors, such as MI-463, MI-503, MI-3454, and VTP-50469, markedly inhibit the proliferation and induce the differentiation of acute leukemia cells and primary patient samples with MLL translocations or NPM1 mutations." (PMID 40837414, 2025). "Results of the phase 1/2 first-in-human clinical trials testing Revumenib and Ziftomenib in patients with MLL1-r and NPM1-mut acute leukemias revealed promising outcomes with an over 30% rate of complete remission." (PMID 39276940, 2024). "Menin inhibitors constitute a novel class of agents targeting the underlying biology of nucleophosmin (NPM1) mutant and KMT2A rearranged (KMT2A acute leukemias." (PMID 38539426, 2024). "The interaction between menin and MLL1 has been implicated in the development of acute leukemias driven by MLL1/KMT2A rearrangements (MLL1-r), NPM1 mutations (NPM1-mut), and NUP98 rearrangements (NUP98-r)." (PMID 39276940, 2024). "The promising preliminary results of AUGMENT-101 prompted the opening of AUGMENT-102 (NCT05326516), a phase 1 trial investigating revumenib in combination with chemotherapy in patients with KMT2A-r or NPM1-m acute leukemias." (PMID 39179671, 2024). "For decades, menin has been appreciated as a potent tumor promoter in MLL-rearranged (MLLr, also known as KMT2Ar) and nucleophosmin 1 (NPM1) mutant acute leukemias." (PMID 39336822, 2024). "KMT2A mutations occur in 5–15% of patients with acute leukemia, while NPM1 is more frequent occurring in nearly 30% of patients with acute leukemia." (PMID 37835461, 2023). "Several menin–MLL inhibitors display potent anti-leukemic activities in preclinical mouse models for MLL-rearranged and NPM1 mutant acute leukemias." (PMID 35941657, 2022). "Here, we will discuss the normal biological roles of menin in acute leukemia, notably in KMT2A translocations and NPM1 mutation, as well as current drug development." (PMID 36497385, 2022). "We showed that the NPM1 gene and its predominant transcripts are increased in acute leukemia when compared to healthy control samples." (PMID 30126426, 2018). "Their upregulation in AML and ALL, decrease after therapy and association with patient outcome suggests the involvement of elevated NPM1 expression in the acute leukemia pathogenesis." (PMID 30126426, 2018). "The aim of this work was to quantify NPM1 transcripts in two types of acute leukemia, derived from different hematopoietic cell lineages: AML and ALL (acute lymphoblastic leukemia)." (PMID 30126426, 2018). "We have discovered that autophagy is activated in acute leukemia cells expressing mutant nucleophosmin 1 (NPMc+) or MLL-fusion proteins." (PMID 27732946, 2016). "Notably, both variants of DS-1594a were highly effective in eradicating tumors and enhancing survival in MOLM-13 cells and xenograft models of KMT2A-r or NPM1-m acute leukemia derived from patients." (PMID 40361241, 2025). "Furthermore, a phase I study sponsored by the City of Hope Medical Center is investigating the safety and tolerability of revumenib as a maintenance therapy in patients (>2 years old) with KMT2A-r or NPM1-m acute leukemia after HSCT (NCT06575296)." (PMID 41154380, 2025). "Importantly, these promising responses are observed across multiple types of acute leukemias driven by multiple different MLL fusion proteins or NPM1 mutants." (PMID 39336822, 2024). "Therefore, the aim of the study was to quantify alternative NPM1 transcripts in two types of acute leukemia, AML and ALL (acute lymphoblastic leukemia)." (PMID 30126426, 2018).
acute leukemia (continued). "Our results confirmed the increase of all three NPM1 transcripts in acute leukemia." (PMID 30126426, 2018). "Conversely, NPM1 gene mutations result in genomic instability, loss of tumor suppressor function, inhibition of normal cell apoptosis, upregulation of MYC protein expression, abnormal expression of HOX genes, ultimately leading to the occurrence of acute leukemia." (PMID 39432585, 2024). "Menin (MEN1) is a well-recognized powerful tumor promoter in acute leukemias (ALs) with lysine methyltransferase 2A (KMT2A, previously known as MLL: mixed-lineage leukemia) rearrangements (KMT2Ar) and mutant nucleophosmin 1 (NPM1m)." (PMID 39796769, 2025). "Bleximenib, for instance, is currently being tested in a pediatric cohort (12 years and older) of the phase 1/2 study (cAMeLot-1) for acute leukemia patients harboring KMT2A, NPM1, NUP98, or NUP214 alterations (NCT04811560)." (PMID 41154380, 2025). "We have discovered that HEXIM1 and NPM1/NPMc+ proteins, key regulators of BET activity, are degraded through the process of autophagy in a number of acute leukemia cell lines and primary cells that express NPMc+ or MLL fusion proteins." (PMID 27732946, 2016). "Consequently, thirty patients found to carry an NPM1 mutation were re-classified as having AML with NPM1 mutation, given that under the updated classification the presence of this mutation is sufficient for a diagnosis of acute leukemia, irrespective of bone marrow blast percentage." (PMID 41283234, 2025).
breast carcinoma (33 papers, 2005 to 2025). "Lower NPM1 level associate with poor prognosis as studied among a cohort of 1160 breast cancer patient samples." (PMID 32257110, 2020). "In breast cancer, low NPM1 levels are also associated with poor outcome, independently of the molecular subtype, with granular staining of NPM1 correlating with poor prognosis." (PMID 27553022, 2016). "In a study of human breast cancer, NPM1 was identified as an estrogen-regulated protein associated with acquired estrogen independence by two-dimensional gel electrophoresis analyses." (PMID 25779011, 2015). "Reduced NPM1 protein level was previously associated with poor outcome in some subtypes of breast cancer." (PMID 24410879, 2014). "Similar to these results, NAT10 leads to enhanced transcription and increased expression of PD-L1 by promoting the acetylation of nucleophosmin 1 in different cancer cells, including human breast cancer, melanoma, and colorectal cancer cells." (PMID 40245789, 2025). "that identified pY397 FAK accumulates in the nucleolus of breast cancer cells to drive stabilization of nucleostemin through NPM1 and AKT." (PMID 40458728, 2025). "Similar to our findings, the interaction of APEX1 and NPM1 has also been reported by previous research in breast cancer and this interaction contributes to drug resistance in triple negative breast cancer." (PMID 38360860, 2024). "NPM1 has been reported to be upregulated in various human cancers, including breast cancer, colorectal cancer, lung cancer, and ES, which promotes cell proliferation and apoptosis resistance." (PMID 38287009, 2024). "For instance, APEX1 overexpression is positively correlated with cancer progression, whereas NPM1 is known as a poor prognostic factor in breast cancer patients." (PMID 36672349, 2023). "APE1 and its interactor, NPM1, protect cancer cells from cytotoxicity from platinum compounds in claudin-low breast cancer." (PMID 36685583, 2022). "Among these, epigenetic modifiers that were previously implicated in breast cancer cell fitness, such as PRMT5, HDAC3, NPM1 were depleted in MDA-MB-231 cells serving as positive controls." (PMID 35973998, 2022). "In breast cancer, colon cancer, and other cancers, overexpression of NPM1 often results in a poor prognosis prediction for patients." (PMID 34899858, 2021). "In fact, NPM1 expression has been found to be higher among basal breast cancer patients than luminal." (PMID 32257110, 2020). "The Kaplan–Meier survival curves showed that breast cancer patients with NPM1 high expression had shorter OS, which indicated that NPM1 was a poor prognostic factor in breast cancer." (PMID 32245950, 2020). "For the preneoplastic (MCF10.AT1) to DCIS (MCF10.DCIS) transition in breast cancer development, GNF2_NPM1 and GGCAGTG_MIR3243P were the top two pathway networks that were found to be significantly dysregulated (by at least twofold)." (PMID 32204397, 2020). "Real time expression from tissue samples has shown higher NPM1 expression in breast cancer (n = 1097) samples than normal (n = 114)." (PMID 32257110, 2020). "NPM1 knockdown has been shown to significantly decrease nuclear factor-κB-mediated invasion of breast cancer cells." (PMID 30061177, 2018). "The decrease of the NPM1 levels upon treatment was also demonstrated in liver cancer, breast cancer and lung cancer cells." (PMID 30126426, 2018). "Our finding is consistent with higher NPM1 expression observed in various cancer types, including prostate adenocarcinoma, lung adenocarcinoma, colorectal cancer, pancreatic ductal adenocarcinoma, breast cancer, and bladder cancer." (PMID 40705480, 2025). "Notably, in MCF-7 breast cancer cells, H1X formed a layer at the nucleolar rim, adjacent to NPM1, similar to what was observed in T47D cells." (PMID 38530350, 2024).